USP9X (ubiquitin specific peptidase 9 X-linked)
Diseases named in the same sentence as USP9X in open-access papers (continued):
Sharing a sentence is not in itself a finding about the gene and the disease.
prostate carcinoma (21 papers, 2014 to 2025). A carcinoma that arises from epithelial cells of the prostate gland. "There is a direct evidence suggesting that a deubiquitinase namely ubiquitin-specific peptidase 9, X-linked (USP9X) can regulate the ERG protein expression in prostate cancer VCaP cells." (PMID 24739220, 2014). "We confirmed this stabilizing effect of USP9x on Mcl-1, particularly in LNCaP prostate cancer cells." (PMID 37173959, 2023). "Of these examined tissue probes, 45 prostate cancer samples and 10 benign prostate tissue samples were used to correlate Mcl-1 and USP9x levels." (PMID 37173959, 2023). "Here, we analyzed the role of anti-apoptotic Mcl-1 and USP9x, a deubiquitinase stabilizing Mcl-1 protein levels, in prostate cancer progression and response to radiotherapy." (PMID 37173959, 2023). "We demonstrate that protein levels of deubiquitinase USP9x and anti-apoptotic Mcl-1 increased during prostate cancer progression." (PMID 37173959, 2023). "In summary, our experiments revealed that deubiquitinase USP9x is able to regulate sensitivity to radiotherapy by increasing Mcl-1 levels, thereby elevating the threshold for apoptosis induction in prostate cancer cells." (PMID 37173959, 2023). "Here, we evaluated protein levels of Mcl-1 and USP9x, a deubiquitinase regulating Mcl-1 protein stability, in human tissue samples during prostate cancer progression." (PMID 37173959, 2023). "Especially at advanced prostate cancer stages, increasing numbers of specimens displayed increased USP9x immunoreactivity together with increased Mcl-1 immunoreactivity." (PMID 37173959, 2023). "Our findings suggest that deubiquitinase USP9x is responsible for upregulated Mcl-1 protein levels, thereby contributing to prostate cancer progression and therapy resistance." (PMID 37173959, 2023). "So far, our results demonstrated that USP9x controls Mcl-1 protein levels and, in this way, regulates the response to radiotherapy in prostate cancer cells." (PMID 37173959, 2023). "We demonstrated a concurrent upregulation of Mcl-1 and USP9x protein levels during prostate cancer progression." (PMID 37173959, 2023). "Since high Mcl-1 protein levels often coincided with high USP9x protein levels at higher stages during prostate cancer progression, a posttranslational stabilization by USP9x provides here a credible explanation for elevated Mcl-1 levels." (PMID 37173959, 2023). "Downregulation of Mcl-1 or USP9x levels improved the response of prostate cancer cells to radiotherapy." (PMID 37173959, 2023). "We detected increased protein levels of deubiquitinase USP9x, an enzyme known to increase Mcl-1 protein stability, during prostate cancer progression, which was positively correlated with Mcl-1 levels." (PMID 37173959, 2023). "In vitro prostate cancer cell line studies showed that the depletion of USP9X resulted in increased cell migration and invasion, which was achieved by the upregulated expression of ERK-mediated MMP9 and phosphorylated dynamin-related protein 1 (DRP1)." (PMID 35884607, 2022). "We show that Usp9x/DUB inhibitor induced apoptosis in ERG independent prostate cancer lines (DU-145, PC-3 NE-like) and NEPC cell line (H660) through the down regulation of SOX2 and also impedes the formation of colonies in 3D-culture." (PMID 33613844, 2021). "Collectively, these results suggest that not only in melanoma, but also in prostate cancer SOX2 expression is controlled via Usp9x." (PMID 33613844, 2021). "In the present study, we identified a deubiquitinase, USP9X as a novel IRS-associated protein, and elucidated its physiological roles in control of IGF signaling and growth of PC3 human prostate cancer cells." (PMID 30338032, 2018). "In a human prostate carcinoma cell line, small interfering RNA (siRNA)-mediated knockdown of USP9X reduced IGF-IR as well as IRS-2 protein levels and increased their ubiquitination." (PMID 30338032, 2018).
prostate carcinoma (continued). "Taken all together, our findings indicate that USP9X is required for the promotion of prostate cancer growth by maintaining the activation of the Erk1/2 pathway through IRS-2 stabilization." (PMID 30338032, 2018). "Knockdown of USP9X significantly reduced anchorage-independent cell growth of prostate carcinoma cell line." (PMID 30338032, 2018). "Previously, we found that ERG undergoes ubiquitination and then is deubiquitinated by USP9X in prostate cancer cells to prevent its proteasomal degradation." (PMID 27626314, 2016). "Negative regulation of pVHL by USP9X was further validated in the human prostate cancer cell line PC3 and the mouse melanoma cell line B16 (lane 1 versus lanes 2-3)." (PMID 27517496, 2016). "A recent study focused on Usp9X in the context of a frequent prostate carcinoma-related genetic translocation (TMPRSS2-ERG) that facilitates tumor growth and thus not only represents a diagnostic aid, but also a potential therapeutic target." (PMID 26008975, 2015). "Moreover, we demonstrated that deubiquitinase USP9x as a factor regulating Mcl-1 levels in prostate cancer cells, thus limiting cytotoxic response to radiotherapy." (PMID 37173959, 2023). "While USP9X gene expression was slightly but insignificantly lower in prostate cancer tissue compared to normal prostate tissue, USP9x protein levels also increased during prostate cancer progression." (PMID 37173959, 2023). "Next, we irradiated prostate cancer cells with 0 or 10 Gy 48 h after transfection with USP9x siRNA." (PMID 37173959, 2023). "Furthermore, we provided insights into the mechanism by which USP9x regulates prostate cancer cell survival." (PMID 37173959, 2023). "During prostate cancer progression, the function of USP9x—as well as its specificity and affinity to its interacting partner molecules—might change, thereby affecting the survival of patients with prostate cancer." (PMID 37173959, 2023). "Furthermore, we detected that high USP9X gene expression correlated with a worse outcome in patients with prostate cancer, although USP9X gene expression was slightly but insignificantly lower in prostate cancer tissues than in normal tissue." (PMID 37173959, 2023). "Finally, we want to point out that our experiments analyzing USP9x-mediated Mcl-1 stability were carried out in two prostate cancer cell lines only." (PMID 37173959, 2023). "We, therefore, hypothesized that the deubiquitinase USP9x contributes to prostate cancer progression by controlling Mcl-1 protein stability." (PMID 37173959, 2023). "Mcl-1 and USP9x immunoreactivity increased with prostate cancer progression." (PMID 37173959, 2023). "Interestingly, it has been shown in prostate cancer cells that the deubiquitinase USP9X interacts with ERG and promotes its stabilisation to decrease prostate cancer cell proliferation." (PMID 35723257, 2022). "Furthermore, ERG was deubiquitylated by USP9X thus stabilized protein levels in prostate cancer cells." (PMID 34112167, 2021). "To assess the downstream effects of knocking down USP9X and USP9Y on a transcriptome-wide scale, we have conducted microarray profiling experiments using the human DU145 prostate cancer cell culture model, after confirming the robust expression of both USP9X and USP9Y in this model." (PMID 31294067, 2019). "Thus, it is likely that at least in a portion of human prostate cancer, USP9X interacts with IRS-2 resulting in its deubiquitination and stabilization, followed by the maintenance of high protein level of IRS-2." (PMID 30338032, 2018). "Our previous discovery of USP9X as an ERG-stabilizing deubiquitinase suggests that reduction of ERG protein levels by TRIM25-mediated proteasomal degradation is prevented by expression of USP9X in fusion-positive prostate cancer cells." (PMID 27626314, 2016).
prostate carcinoma (continued). "Usp9X remains an interesting target as its levels are increased in glioblastoma and this molecule maintains high levels of certain anti-apoptotic factors, such as Mcl-1, Inhibitor of Apoptosis Proteins and a gene fusion observed in 40% of prostatic carcinomas." (PMID 26474387, 2015). "Thus, we now confirmed USP9x as a radioprotective factor in prostate cancer cells." (PMID 37173959, 2023). "High USP9X gene expression was associated before with shorter survival of patients with follicular lymphoma, esophageal squamous cell carcinoma, non-small cell lung cancer, and osteosarcoma, but not with the survival of patients with prostate cancer." (PMID 37173959, 2023). "The moderate and highly significant positive correlation between Mcl-1 and USP9x immunoreactivity (Spearman’s r = 0.560, p = 0.000043; Pearson’s r = 0.510, p = 0.00025) proposed an interrelation between the anti-apoptotic protein Mcl-1 and the deubiquitylating enzyme USP9x in prostate cancer." (PMID 37173959, 2023). "Similarly, ERG degradation is induced by Usp9x inhibitor WP1130 in prostate cancer." (PMID 33613844, 2021). "In addition, USP9X interacted with endogenous IRS-1/2 in PC3 human prostate cancer cells." (PMID 30338032, 2018). "Finally, Usp9x KD in ERG-positive prostate cancer cells (VCaP) reduced NRAS protein content." (PMID 28198367, 2017). "Thus, overexpression of ERG in prostate cancer may cause an increase in TRIM25 activity, which is mitigated by the expression of the deubiquitinase USP9X, which is required to stabilize ERG." (PMID 27626314, 2016). "To examine the interaction between the anti-apoptotic protein Mcl-1 and USP9x in more detail, we employed LNCaP and PC3 prostate cancer cell lines." (PMID 37173959, 2023). "In this context, previous publications demonstrated that USP9x-dependent stabilization of insulin receptor substrate 2 or the transcription factors PBX homeobox 1 and ERG supported prostate cancer growth and metastasis." (PMID 37173959, 2023). "In particular, we examined the posttranslational regulation of Mcl-1 protein levels by USP9x and the relevance of this mechanism for cell survival in human LNCaP and PC3 prostate cancer cells." (PMID 37173959, 2023). "On the other hand, there are other DUBs, such as USP9X and UCHL3, that reduce their expression in prostate cancers." (PMID 35884607, 2022). "In this study, our findings provided the first evidences that USP9X regulates the protein level of IRS-2, and therefore regulates the IGF-IR/IRS-2/Erk1/2 axis in PC3 human prostate cancer cells." (PMID 30338032, 2018). "In prostate cancer cells USP9X has been found to deubiquitinate and stabilise ERG, while increasing expression of USP9X was found to correlate with higher grade and poorer outcome in oesophageal squamous cell carcinomas." (PMID 26506417, 2015). "Targeting Mcl-1 or USP9x improved the response of LNCaP and PC3 cells to radiotherapy and might prove beneficial for prostate cancer patients receiving radiotherapy." (PMID 37173959, 2023). "Although the analysis of gene expression did not allow a distinction between different stages during prostate cancer progression, the gene expression data do not match with our results obtained from the immunohistological detection of USP9x." (PMID 37173959, 2023). "A possible interaction between Mcl-1 and USP9x was examined in LNCaP and PC3 prostate cancer cells." (PMID 37173959, 2023). "Although MCL1 expression did not affect the survival of patients with prostate cancer, expression data suggests a more prominent role for the deubiquitinase USP9x." (PMID 37173959, 2023). "Treatment of prostate cancer cells with the USP9X inhibitor WP1130 resulted in ERG degradation both in vivo and in vitro, impaired the expression of genes enriched in ERG and prostate cancer relevant gene signatures, and inhibited growth of ERG-positive tumors in mouse xenograft models." (PMID 33634124, 2021).
prostate carcinoma (continued). "Usp9x deubiquitinates and stabilizes the TF, ERG, in prostate, and we previously published that DUB inhibitor (WP1130) has anti-tumor activity in ERG fusion driven prostate cancer." (PMID 33613844, 2021). "In addition, by using PC3 human prostate cancer cells, we revealed that IRS-2 stabilization by USP9X is required for the constitutive activation of Erk1/2." (PMID 30338032, 2018). "In another cohort of 90 prostate cancer patients and 83 melanoma patients, individuals with metastatic cancer showed significantly higher USP9X levels than individuals with primary cancer and no metastases (melanoma, p < 0.0001; prostate, p = 0.0037)." (PMID 27517496, 2016). "Although not all prostate cancer cells might use USP9x to stabilize Mcl-1, USP9x might account for elevated Mcl-1 levels, particularly in advanced prostate cancer." (PMID 37173959, 2023). "In addition, USP9X is known to regulate the invasion of prostate cancer cells by inducing ERK‐mediated Drp1 phosphorylation, but not the stability, suggesting that deubiquitinase may affect the phosphorylation of Drp1 and mitochondrial dynamics." (PMID 33070427, 2020). "Thus, the expression of TRIM25 in prostate cancer cells may not result in reduced ERG protein levels when USP9X is also expressed." (PMID 27626314, 2016). "Interestingly, we detected an association between patient survival and gene expression of USP9X only, but not of HUWE1, BTRC, and FBXW7, even though all gene products are able to interact with Mcl-1, further emphasizing the role of the deubiquitinase in prostate cancer progression." (PMID 37173959, 2023).
lung carcinoma (20 papers, 2011 to 2025). "Additional functional experiments revealed that USP9X-deficient lung cancer cells formed longer comet trails, fewer Rad51 foci, and exhibited enhanced radiosensitivity after radiation exposure." (PMID 38802791, 2024). "More importantly, we found that MG132 treatment substantially rescued the decline in KDM4C protein caused by USP9X depletion in lung cancer cells, implying that USP9X protects KDM4C from degradation by the proteasome." (PMID 33558705, 2021). "We further observed that loss of USP9X suppressed the growth and proliferation of lung cancer cells, and these defects were partially restored by overexpression of KDM4C." (PMID 33558705, 2021). "Importantly, overexpression of REV1 in USP9X-deficient lung cancer cells was able to reverse the upregulation of CTH expression." (PMID 38802791, 2024). "Furthermore, we revealed that the aberrant high expression of REV1 in lung cancer is caused by USP9X-mediated deubiquitination modifications." (PMID 38802791, 2024). "In this study, we report for the first time that the high REV1 expression in lung cancer is associated with the deubiquitinase USP9X and that abnormally high REV1 expression can act as a scaffolding protein to assist the E3 ubiquitin ligase Rad18 binding to the substrate CTH." (PMID 38802791, 2024). "We found USP9X overexpressed in lung cancer, suggesting that this event might be linked to the expansion of the cancer stem cell compartment in this tumor: a possibility that warrants further investigation." (PMID 21283576, 2011). "USP9X-mediated KDM4C deubiquitylation promotes lung cancer radioresistance by epigenetically inducing TGF-β2 transcription." (PMID 40246814, 2025). "USP9X-mediated deubiquitination of KDM4C epigenetically induces TGF-β2 transcription to drive radioresistance in lung cancer." (PMID 41488674, 2025). "Taken together, these data suggest that USP9x is highly expressed in lung cancer tissues and its expression promotes tumor growth." (PMID 39075050, 2024). "USP9X enhances the deubiquitination of KDM4C to elevate radioresistance of lung cancer cells by activating the TGF‐β2/Smad signaling." (PMID 39143031, 2024). "Overall, our study uncovers a novel function of USP9x as a regulator of the proline biosynthesis pathway, which impacts lung cancer growth and progression, and implicates a new potential therapeutic avenue." (PMID 39075050, 2024). "Ubiquitination assay results indicated REV1 can be significantly ubiquitinated in lung cancer cells, and the positive regulatory effect of USP9X on REV1 can be reversed by MG132." (PMID 38802791, 2024). "Secondly, to evaluate USP9x protein levels in human lung cancer tissues, IHC staining of 142 LUAD samples of all disease stages was performed." (PMID 39075050, 2024). "While USP39 is largely identified to participate in alternative splicing, the precise role of USP9x in different types of cancer, in particular lung cancer, is less studied." (PMID 39075050, 2024). "By comparing the staining intensities to 92 normal adjacent healthy tissues and normal lung tissues, our IHC analysis revealed that USP9x was specifically expressed in elevated levels in lung cancer tissues." (PMID 39075050, 2024). "In the GEO database, the expression levels of MET, ETS-1, and USP9X in osimertinib-resistant lung cancer cells, as observed in the datasets GSE202859 and GSE236654, were significantly higher than those found in osimertinib-sensitive lung cancer cells." (PMID 39468027, 2024). "Collectively, these data suggest a potential role of USP9x as a positive regulator of metabolism in lung cancer cells." (PMID 39075050, 2024). "By using chemical markers, quantitative proteomic screening and other methods, USP9X RNA interference was analyzed in A549 lung cancer cells before and after, and functional experiments in vitro and in vivo were conducted." (PMID 35784389, 2022).